STAT3 (signal transducer and activator of transcription 3)
Diseases named in the same sentence as STAT3 in open-access papers (continued):
Sharing a sentence is not in itself a finding about the gene and the disease.
melanoma (continued). "In recent years, several articles have pointed out the important role of STAT3 inhibition in apoptosis in melanoma." (PMID 30622697, 2019). "High level of IFN-β activates STAT1, STAT2 and STAT3 to facilitate cellular dormancy in tumor-repopulating melanoma cells." (PMID 30546090, 2019). "Consistent with the effects by C188-9 on NDV/FMW-mediated cell death in melanoma cells, STAT3 depletion also decreased NDV/FMW-triggered PARP cleavage and eIF2α phosphorylation." (PMID 31192135, 2019). "In this study, we found MEK, AKT and STAT3 inhibitors interfered with melanoma cell proliferation and attenuated nicotine-induced melanoma cell proliferation." (PMID 31835799, 2019). "Through an autocrine loop, including the activation of STAT3, IL-6 signaling contributes to survival and proliferation of melanoma cells, increases the metastatic potential, and facilitates immune evasion." (PMID 31269655, 2019). "Overexpression of STAT3β in B16 melanoma cells diminishes STAT3 DNA-binding activity, blocks STAT3-mediated gene expression and reduces cell proliferation." (PMID 31861597, 2019). "The STAT3 protein is often constitutively activated in melanoma cells and its inhibition in melanoma induces cell death, tumour regression and the inhibition of metastatic dissemination." (PMID 31801187, 2019). "The transcription factor STAT3 is often hyperactivated in melanoma and is a potential target for melanoma therapy." (PMID 31192135, 2019). "Transduction of WM9 and UACC903 melanoma cells with STAT3-small hairpin RNA decreased both PDK1 mRNA and protein levels." (PMID 30622697, 2019). "Taken together, G6PD status is linked to cell proliferation and cellular malignancy, possibly through the STAT3/5 ratio, in mice melanoma cells." (PMID 31500396, 2019). "Nevertheless, only minor roles for STAT3 were reported on PD-L1 expression in melanoma cell lines when transiently stimulated with IFN-γ11." (PMID 31406210, 2019). "The dual effect of STAT3 in melanoma, as well as tumor-attacking immune cells, is of great therapeutic interest since STAT3 inhibition not only blocks survival of cancer cells themselves but also boosts the cytotoxic behavior of infiltrating immune cells." (PMID 31569642, 2019). "It has been demonstrated that the high cell density-induced activation of STAT3 in melanoma cells is mediated by JAKs19." (PMID 30679726, 2019). "Our results also established that PDK1 is an important mediator of drug-resistance mediated by STAT3 in melanoma." (PMID 30622697, 2019). "Subsequent studies have determined that the STAT3 decoy can inhibit the growth of a broad variety of cancer cell lines, including cells representing melanoma and cancers of the bladder, brain, breast, colon, liver, lung, and ovary." (PMID 31671769, 2019). "STAT3 becomes inappropriately and constitutively activated in a high percentage of solid malignancies including melanoma, multiple myeloma, and cancers of the breast, ovary, prostate, head and neck, and pancreas." (PMID 31291201, 2019). "To study this mechanism in human melanoma cells using a suitable model we screened several melanoma cell lines to identify those displaying constitutive STAT3 activation." (PMID 30622697, 2019). "High levels of IL6 dramatically promoted tumor invasion and metastasis of murine melanoma by upregulation of transcription activity of STAT3 and production of STAT3-dependent MMP9 in tumor cells." (PMID 31680949, 2019). "It was found that administration of STAT3 inhibitor-loaded polymeric micelles results in apoptotic cell death in melanoma cells and down-regulates VEGF expression." (PMID 31569687, 2019). "While andrographolide enhanced the expression of Bax, caspase-3, and caspase-9, it down-regulated that of Bcl-2, leading to apoptosis in melanoma B16F-10 cells, and it promoted apoptosis in pancreatic cancer cells via inhibition of STAT3 and Akt activation." (PMID 31404237, 2019).
melanoma (continued). "The levels of p-STAT3 is higher in metastasis (particularly brain and lung) than in cutaneous primary melanomas." (PMID 30622697, 2019). "Melanoma cells resistant to PLX-4032 showed increased STAT3 pathway activity, and in vitro silencing of this signaling inhibited the growth of cells resistant to PLX-4032." (PMID 30691132, 2019). "JSI-124 PLGA NPs have great anti-tumor activity against B16 melanoma cells by reducing the expression of STAT3 in DCs and enhancing the function of DCs in terms of promoting the production of T cells leading to the cancer immunotherapy." (PMID 31569687, 2019). "The constitutive activity of STAT3 in melanoma contributes to increase the expression level of PDK1 which, in turn phosphorylate and activate AGC kinases including Akt, PKC, and SGK." (PMID 30622697, 2019). "STAT3 is highly upregulated in melanoma, and its activation by phosphorylation contributes to cancer progression and survival." (PMID 30691132, 2019). "XBP1 has been implicated in the regulation of melanoma cell proliferation by activating inteleukin-6/STAT3 pathway in addition to its critical role in melanoma cell survival during ER stress." (PMID 30989459, 2019). "STAT3 inhibitors have demonstrated their efficacy in animal tumor models and are currently under ongoing clinical trials for melanoma treatment (ClinicalTrials.gov Identifiers: NCT01904123, NCT03195699)." (PMID 31569642, 2019). "The IL-6/JAK1/signal transducer and activator of transcription 3 (STAT3) axis also controls actomyosin contractility by regulating the levels of phosphorylated-MLC2 in both melanoma cells and CAFs." (PMID 31067787, 2019). "From this evidence, we conclude that STAT3 signaling pathway regulates cell growth and PD-L1 expression in melanoma cells." (PMID 31835799, 2019). "And then IL-6 activated oncogenic STAT3 in melanoma cells and increased expression of prosurvival genes, such as Bcl-2, Bcl-xl." (PMID 30800130, 2019). "STAT3-expressing cancer cells dysregulate immune cells, while at the same time, immune cells with high levels of STAT3 are unable to target melanoma cells." (PMID 31569642, 2019). "In detail, melanoma cells which overexpress STAT3 protein inhibit the expression of proinflammatory cytokines and chemokines, such as VEGF, IL-10, and IL-6." (PMID 31569642, 2019). "In another study, a single injection of lentiviral vectors encoding Stat3-targeting shRNA were able to downregulate Stat3, Survivin, and MMP-2 at the same time impair tumor cell survival and invasiveness in melanoma models." (PMID 30847297, 2019). "A lentiviral vector was constructed to co-express Interferon (IFN) genes and siRNA targeting STAT3 to suppress the proliferation of B16 melanoma cells with over 95% transduction efficiency." (PMID 30847297, 2019). "STAT3 influences the interplay between melanoma cells and components of the immune system, thus contributing to immune evasion." (PMID 31569642, 2019). "It appears that clathrin-mediated endocytosis participates in cellular uptake of STAT3-siRNA-loaded NPs by melanoma cells." (PMID 31569687, 2019). "Direct STAT3 targeting in melanoma cell lines sufficed to modulate these crosstalks and enhanced antitumor activity through increasing interferon gamma (IFNγ) levels, mature dendritic cells, and CD8+ T cells." (PMID 31569642, 2019). "Of note, the transcription factor STAT3 plays a critical role in the induction of ICD in melanoma cells exposed to NDV/FMW." (PMID 31192135, 2019). "Two human melanoma cell lines, A375 and G361, with constitutive activation of STAT3, together with a murine melanoma cell line, B16F10, were employed, showing that inhibition of the STAT3 signaling pathway contributes to the anti-metastatic effect of apigenin." (PMID 31139235, 2019). "There is the first evidence that STAT3 activation in NK cells that trigger innate immune responses by the destruction of the tumor cells, can suppress their cytotoxicity against melanoma cells in vivo." (PMID 31569642, 2019).
melanoma (continued). "PD-L1 expression was upregulated in melanoma cells after nicotine treatment via α9-nAchR-mediated activation of the binding of the transcription factor STAT3 to the PD-L1 promoter." (PMID 31835799, 2019). "p5RHH/STAT3 siRNA nanoparticles mediated transfection to impede malignant cell growth, angiogenesis and foam cell formation in mouse melanoma cells while maintaining their size and transfection effectiveness even there are serum proteins around." (PMID 30847297, 2019). "We show that NDV/FMW triggers ICD in both cultural melanoma cells and in mouse models, which can be modulated by targeting signal transducer and activator of transcription 3 (STAT3)." (PMID 31192135, 2019). "To test this, we first examinedthe activation of STAT3 (tyrosine phosphorylation of STAT3 at Y705) in melanoma cells in response to NDV/FMW infection." (PMID 31192135, 2019). "In conclusion, STAT3 establishes a reciprocal relationship between melanoma cells and immune cells in favor of tumor immune evasion." (PMID 31569642, 2019). "While STAT3 inhibition reactivates NK cells against melanoma, STAT5 inhibition suppresses tumor cytotoxic activities of NK cells." (PMID 31569642, 2019). "Consistent with in vitro, PEI/siRNA showed an effective down regulation of STAT3 mRNA expression in vivo, which was the antitumor molecular mechanism of STAT3 siRNA against melanoma." (PMID 29348670, 2018). "WP1066, one of the most promising STAT3 inhibitor, will be investigated in phase I clinical trial for patients with recurrent malignant glioma and brain metastasis from melanoma (scheduled for 2017, ClinicalTrials.gov)." (PMID 29423098, 2018). "The study is the first to explore the potential of dissolving MNs for delivering STAT3 siRNA into skin in vivo and subsequent anti-melanoma and gene silencing efficacy." (PMID 29348670, 2018). "Increased melanoma adhesion on KO lung endothelial cells (LEC) was facilitated by increased E-Selectin levels and by increased STAT3-regulated secretion of senescence-associated factors from KO-LF, such as Vegf." (PMID 30323895, 2018). "IDH1 mutants can play a dominant negative role in wild-type IDH1 functions, resulting in the increased phosphorylation of MAPK and signal transducer and activator of transcription 3 in melanoma cells." (PMID 29661250, 2018). "We demonstrated for the first time that dissolving microneedle is an effective and safe strategy for targeting delivery of STAT3 siRNA via skin to melanoma cells and exerts specific anti-melanoma effect." (PMID 29348670, 2018). "They observed that SIPAR physically interacts with STAT3 in melanoma cells and inhibits STAT3 activity by accelerating its dephosphorylation." (PMID 29914167, 2018). "The pro-inflammatory response to melanoma by nF κB and STAT3 pathways makes the cancer cells resist TRAIL-induced apoptosis." (PMID 30157799, 2018). "The enhancement of PI3K/AKT, STAT3, TGFβ/SMAD, chemokines and other signaling processes appears to cause a shift in the phenotype of melanoma cells that permits their metastasis to the brain." (PMID 30053879, 2018). "Recent study showed that suppression of STAT3 signaling had a promoting effect on the anti-melanoma action of AT-II in B16 and A375 cells." (PMID 30505341, 2018). "MAGEC2 was shown to interact with STAT3 and inhibit its polyubiquitination and proteasomal degradation in human and mouse melanoma cell lines (i.e., A375 and B16, respectively)." (PMID 29914167, 2018). "This cascade is over-activated in some types of melanoma, where STAT3 seems to be crucial, triggering the transcription of anti-apoptotic and pro-survival genes." (PMID 30166456, 2018). "The potential oncogenic role of STAT3 was established by the expression of constitutively activated STAT3 in various tumor cell lines including breast, melanoma, pancreas, prostate, colon and esophagus and stomach." (PMID 29636641, 2018).
melanoma (continued). "In both hepatocellular carcinoma and human melanoma cancers, the STAT3 transcription factor leads to the survival, proliferation, invasion, and angiogenesis of human carcinoma by regulating the subsequent expression of target cancer genes involved." (PMID 30250008, 2018). "Overexpression of SIPAR in the murine melanoma cell line B16 inhibited the expression of STAT3 target genes and cell growth in vitro and repressed melanoma progression in nude mice." (PMID 29914167, 2018). "STAT3 is hyperactive in melanoma, its abnormal activation promotes tumor cell proliferation, suppresses apoptosis, and induces invasion and metastasis; therefore, silencing STAT3 gene by siRNA is a promising strategy for treating melanoma." (PMID 29348670, 2018). "The gene silencing effects of PEI/siRNA on STAT3 mRNA expression in vivo was the antitumor molecular mechanism of STAT3 siRNA against melanoma." (PMID 29348670, 2018). "Hyperactivity of signal transducer and activity of transcription 3 (STAT3) plays a crucial role in melanoma invasion and metastasis." (PMID 29348670, 2018). "This indicated that STAT3-dependent signaling played a role in regulating processes that mediate the invasion and angiogenesis of metastatic melanoma cells to the brain." (PMID 30053879, 2018). "In Oncomine analysis, STAT3 was found to be unregulated in brain and CNS, gastric, head and neck, melanoma, myeloma cancer, but deregulated in breast, leukemia, liver, lymphoma, and sarcoma cancer." (PMID 29423040, 2018). "Some studies on melanoma have shown that STAT3 increases the expression of antiapoptotic genes Bcl-xl, Mcl-1 and further promote melanoma proliferation and malignant transformation." (PMID 29348670, 2018). "In vivo experiments indicated that topical application of STAT3 siRNA PEI complex delivered by dissolving MNs into skin can effectively suppress the development of melanoma through silencing STAT3 gene, and the inhibition effect is dose-dependent." (PMID 29348670, 2018). "It is well recognized that constitutive activation of STAT3 plays a critical role in melanoma development." (PMID 28596565, 2017). "For instance, it was also reported that insulin signaling negatively regulates Stat3 transcription in human melanoma cells." (PMID 29146985, 2017). "Ectopic expression of IRE1α and XBP1s in melanocytes and melanoma cells increased IL-6 levels and then activated intracellular STAT3 signaling, which was diminished by the addition of IL-6 antibodies." (PMID 28222747, 2017). "Differentiation of IL-10-producing regulatory DC has also been shown to be driven by autocrine IL-6/IL-10 signaling through STAT3 in DC, which is initiated by melanoma-derived factors that activate the TLR2 signaling pathway in these cells." (PMID 29209327, 2017). "Persistent activation of STAT3 has been shown to mediate several oncogenic features in many types of cancers, including melanoma." (PMID 28129639, 2017). "STAT3, persistently activated in melanoma, has been shown to regulate the transcription of a panel of genes involved in several oncogenic features, such as cell proliferation, apoptosis and metastasis." (PMID 28596565, 2017). "Emerging evidence also show an anti-inflammatory function of PF4 in melanoma and multiple myeloma through inhibition of STAT3 and upregulation of SOCS3 mediated mechanisms." (PMID 27223426, 2017). "SLE also inhibited cell viability, induced cell apoptosis, restrained cell migration and invasion, suppressed STAT3 activation and nuclear localization, and downregulated STAT3 target genes in melanoma cells." (PMID 28596565, 2017). "Constitutively active signal transducer and activator of transcription 3 (STAT3) has been proposed as a therapeutic target in melanoma." (PMID 28596565, 2017). "Involvement of the MEK/ERK/STAT3 pathway has been reported to suppress the ultraviolet B-induced apoptosis in melanoma." (PMID 29340087, 2017).
melanoma (continued). "The JAK2/STAT3 signaling pathway plays a critical role in tumorigenesis, and has been suggested as a potential molecular target for anti-melanoma therapeutics." (PMID 28570563, 2017). "Previous study has indicated that miR-125b expression is down-regulated in melanoma, and Stat3 is a downstream target of miR-125b." (PMID 28108732, 2017). "Immunoblotting assay was employed to further determine the effects of SLE on STAT3 activation in melanoma cells." (PMID 28596565, 2017). "To further validate the contribution of STAT3 signaling in the anti-melanoma effects of SLE, we established A375 stable cells persistently expressing STAT3C, a constitutively active variant of STAT3." (PMID 28596565, 2017). "Our results suggested that in melanoma cells, the constitutive activation of STAT3 is activated by secreted extracellular IL-6 working in an autocrine/paracrine manner, which can be abolished by adding IL-6 antibodies to the medium, thus neutralizing IL-6." (PMID 28222747, 2017). "For example, 6-bromoindirubin-3’-oxime inhibits STAT3 signaling and induces apoptosis of human melanoma cells, and the STAT3 inhibitor WP1066 attenuates miRNA-21 to suppress human oral cancer growth in vitro and in vivo." (PMID 29207645, 2017). "Intragastric administration of SLE (1.2 g/kg) potently inhibited melanoma growth in mice and inhibited STAT3 phosphorylation in the tumors." (PMID 28596565, 2017). "Our group demonstrated that IL-6, a TLR signaling product, can activate STAT3 with resulting overexpression of Wnt5a in human papillary thyroid carcinoma, melanoma and pancreatic cancer." (PMID 29371911, 2017). "In conclusion, our data indicated that FAK inhibited the expression of E-cadherin via p-SrcY416/p-ERK1/2/ p-Stat3Y705 and PPARγ/miR-125b/Stat3 signaling pathway in both melanoma cells and human tumors." (PMID 28108732, 2017). "STAT3 level was decreased in human melanoma WM793 cells treated with the Les-3833 for 72 h, while the doxorubicin did not affect the level of this transcription factor." (PMID 28409496, 2017). "Our previous report showed that FAD104 suppressed the TGF-β–independent migration of melanoma cells by inhibiting activation of the STAT3 signaling pathway." (PMID 29180690, 2017). "BBMD3, another JAK2 inhibitor, which inhibited autophosphorylation of JAK2 and blocked activation of downstream STAT3 signaling in melanoma cells." (PMID 28570563, 2017). "High levels of acetyl-STAT3 (K685) was also found in many types of cancers including melanomas, colon cancers and TNBCs." (PMID 29137356, 2017). "STAT3 activation also promotes melanoma metastasis via increasing the expressions of vascular endothelial growth factor (VEGF), MMP-2 and MMP-914, 32–34." (PMID 28596565, 2017). "In our previous studies, it was found that quercetin, one of the bioflavonoids occurring in both SF and LJF, exhibited anti-melanoma action partially by inhibiting STAT3 signaling." (PMID 28596565, 2017). "miR-204 is under the control of STAT3 and its expression is induced in amelanotic melanoma cells, where it acts as an effector of vemurafenib's anti-motility activity by targeting AP1S2." (PMID 28445987, 2017). "Our results suggested that FAK inhibited E-cadherin expression via miR-125b/Stat3 signaling pathway in B16F10 melanoma cells." (PMID 28108732, 2017). "Treatment of MK-2206, an AKT inhibitor, alone or U0126, a MEK inhibitor, alone for 1 h markedly increased STAT3 phosphorylation at tyr705 site in human melanoma A375S and A2058 cells." (PMID 27323414, 2016). "In the present study, we examined the involvement of the STAT3 signaling pathway in the anti-metastatic effect of apigenin in melanoma." (PMID 26911838, 2016). "We also observed that IT treatment for 1 h significantly increased the phosphorylated STAT3 (ser727) in human melanoma A375S and A2058 cells, while MK-2206 or U0126 pretreatment for 1 h partially reversed IT(40 μM)-inducedSTAT3 phosphorylation at ser727 site." (PMID 27323414, 2016).